FLI1 (Fli-1 proto-oncogene, ETS transcription factor)
Diseases named in the same sentence as FLI1 in open-access papers (continued):
Sharing a sentence is not in itself a finding about the gene and the disease.
Ewing sarcoma (continued). "Together, our studies show that the EWS/Fli1-repressed miR-193b is growth suppressive in Ewing Sarcoma, and identify ErbB4 as a target gene and candidate mediator of this growth suppression." (PMID 28542597, 2017). "YK-4-279, a small molecule that blocks the interaction between FLI1 and RNA helicase A, was tested in a Ewing sarcoma cell line xenograft and induced tumor regression with daily dosing." (PMID 27732970, 2017). "Recent studies, however, have documented that FLI1 is also aberrantly expressed in several solid tumors, including Ewing sarcoma, metastatic melanomas and nasopharyngeal carcinoma." (PMID 28410216, 2017). "Eight microRNAs (143, 153, 184, 193b, 195, 203, 206 and 223) were selected for evaluation as EWS/Fli1-repressed and underexpressed in Ewing Sarcoma cells, and reported to be growth suppressive in other pediatric or/and adult cancers." (PMID 28542597, 2017). "An in-depth study also demonstrates that FLI1 is able to induce apoptosis and growth arrest through the activation of Caspase3 in some primary Ewing sarcoma cells." (PMID 28410216, 2017). "The ERG related members include ETV1, ETV4, ETV5 and FLI1 which have been shown to overexpress in different diseases including CaP, Ewing sarcoma, and acute myeloid leukemia." (PMID 28191285, 2016). "This translocation leads to the gene fusion between the 5′ segment of the EWSR1 gene (Ewing sarcoma breakpoint region 1) on the chromosome 22 and the 3′ portion of Fli1 (Friend leukemia virus integration site 1), located on the chromosome 11." (PMID 27006472, 2016). "EWS (Ewing sarcoma region 1, EWSR1) was originally identified as part of a fusion gene with FLI1, in Ewing sarcoma cells." (PMID 27557633, 2016). "In Ewing’s sarcoma the fusion protein EWS/FLI1 inhibits basal and β-catenin induced transactivation of the DKK1 promoter." (PMID 27539223, 2016). "The IGF-1 pathway is functionally important for the pathogenesis and progression of Ewing Sarcoma and the fusion protein EWS/FLI1 has been shown to downregulate the expression of IGFBP3 in Ewing sarcoma cell lines." (PMID 27539223, 2016). "While EWS/FLI1 plays a central role in orchestrating expression of oncogenic mediators in Ewing sarcoma, it remains a challenging drug target." (PMID 26337082, 2015). "The fact that GLI1 expression is constitutively induced by EWS/FLI1 in Ewing sarcoma suggests that drugs acting upstream GLI1 will be ineffective in blocking this pathway in this cancer." (PMID 26258070, 2015). "The study of the mechanism through which EWS/FLI1 upregulates DAX-1 expression in Ewing sarcoma cells revealed an unexpected finding: EWS/FLI1 directly interacts with DAX-1 promoter through binding to a GGAA-rich sequence." (PMID 26258070, 2015). "Four EWS/FLI1-rearranged Ewing sarcoma cell lines (A673, EW8, EWS502, and TC71) and one EWS/ERG-rearranged cell line (CADO-ES-1) were included in the screen." (PMID 26337082, 2015). "Recently, it has been shown that EWS/FLI1 utilizes divergent chromatin remodeling mechanisms to directly activate or repress enhancer elements in Ewing sarcoma." (PMID 26337082, 2015). "In order to study the role of the EWS/FLI1 oncogenic transcription factor in maintaining super-enhancers specifically in Ewing sarcoma, we set up a Mir30-shRNA-mediated doxycycline-inducible EWS/FLI1 knockdown system in the Ewing sarcoma cell line TC32." (PMID 26337082, 2015). "Ewing sarcoma is driven by EWS/FLI1, which is a protein generated by a tumor-specific aberrant translocation." (PMID 26258070, 2015). "Another mechanism reported to enhance cyclin D1/CDK4 pathway activation in Ewing sarcoma is via the EWS/FLI1 fusion protein binding the CCND1 gene promoter resulting in increased expression of cyclin D1 protein." (PMID 26337082, 2015). "In the past years, an important effort to identify EWS/FLI1 genes functionally relevant for Ewing sarcoma pathogenesis has been carried out." (PMID 26258070, 2015).
Ewing sarcoma (continued). "Here we report that FLI-1-EWS, a fusion gene reciprocal to EWS-FLI-1, is frequently expressed in Ewing sarcoma." (PMID 26807198, 2015). "Usually Ewing's sarcoma associates an overexpression of the CD99 membrane protein and expression of the friend leukemia virus integration (FLI-1)." (PMID 25922782, 2015). "FLI1 is a master regulator of hematopoiesis in the ETS family, and has been causally implicated in pediatric Ewing’s sarcoma." (PMID 26579211, 2015). "These authors also confirmed using RNAi that the expression of GLI1 in Ewing sarcoma cells (TC71) is dependent on EWS/FLI1 and that GLI1 expression was relevant for the maintenance of the transformed phenotype." (PMID 26258070, 2015). "Our laboratory had previously identified regulation of expression of components of the IGF signaling pathway by EWS/Fli1-controlled microRNAs in Ewing Sarcoma." (PMID 25603314, 2015). "The EWS-FLI1 gene shares the same 3′-UTR with the FLI1 gene; therefore, its relationship with miR-145 has been explored in Ewing's sarcoma." (PMID 25124875, 2014). "FLI1 is a fusion gene that is usually positive in Ewing sarcoma, but some cases of synovial sarcoma also show FLI1 positivity." (PMID 24715974, 2014). "Positivity for LCA in lymphoma, CD99 immunoreactivity and EWS/Fli1 translocation in extraskeletal Ewing sarcoma." (PMID 25253623, 2014). "The translocation results in the fusion of the N-terminal region of the EWS (Ewing’s sarcoma) gene with the DNA binding domain of the proto-oncogene FLI-1 (Friend leukemia integration site 1)." (PMID 25870707, 2014). "A specific small molecule, YK-4_279, can block RHA binding to EWS/FLI1, inducing apoptosis in Ewing sarcoma cells and reducing the growth of tumor cell in mice." (PMID 23329308, 2013). "During the last years, important efforts have been made to identify gene targets of the EWS/FLI1 oncoprotein in Ewing sarcoma cells." (PMID 23750284, 2013). "The reciprocal genomic FLI1-EWS fusion sites (der11) were detected in 27/42 Ewing sarcoma patients and five out of seven cell lines (overall 65%)." (PMID 23441188, 2013). "Our previous studies profiling miRs downstream of the EWS/Fli1 fusion oncoprotein identified several members of the miR 17∼92a, 106b∼25 and 106a∼363 clusters as candidate upregulated miRs in Ewing Sarcoma." (PMID 23638178, 2013). "It has been recently demonstrated, using cellular models, that EWSR1/FLI1 is able to block the ability of Runx2 in order to induce osteoblast differentiation, responsible of Ewing tumor pathogenesis." (PMID 23329308, 2013). "During the last years we have used an inducible model of EWS/FLI1 knockdown in combination with whole gene expression analysis to identify and characterize EWS/FLI1 target genes relevant for Ewing sarcoma tumorigenesis." (PMID 23750284, 2013). "Analysis of our gene expression profile dataset in the Ewing sarcoma cell line A673 upon EWS/FLI1 knockdown showed that one of the most strongly downregulated genes by EWS/FLI1 codes for the enzyme lysyl oxidase (LOX)." (PMID 23750284, 2013). "The fusion transcript EWSR1/FLI1 is present in more than 90 % of the Ewing sarcomas, and in the related group of peripheral primitive neuroectodermal tumor (pPNET), in rhabdomyosarcoma, in neuroblastoma and in giant cell tumor of bone." (PMID 23329308, 2013). "A majority of Ewing sarcomas contain a translocation that fuses the EWS gene on chromosome 22 to the FLI1 gene on chromosome 11." (PMID 23894528, 2013). "Microarray studies and real time quantitative RT-PCR demonstrated that LOX mRNA was downregulated by the EWS/FLI1 oncoprotein in the A673 Ewing sarcoma cell line." (PMID 23750284, 2013). "Specifically, they compared the miR profiles of CD133+ and CD133− subpopulations from two Ewing Sarcoma tumors, pediatric MSCs stably expressing retrovirally introduced EWS/Fli1, and one Ewing Sarcoma cell line (STA-ET-8.2)." (PMID 23543617, 2013).
Ewing sarcoma (continued). "The prototype rearrangement between chromosomes 11 and 22 produces an EWS/FLI1 fusion which is found in over 85% of Ewing tumors." (PMID 23365673, 2013). "MiR-145 was the miR most consistently changed, namely reduced upon EWS/Fli1 depletion, and underexpressed in Ewing Sarcoma relative to MSCs." (PMID 23543617, 2013). "In humans, Fli1 is frequently involved in the development of Ewing sarcoma and related subtypes of primitive neuroectodermal tumors, suggesting that Fli1 plays an important role in the process of cellular transformation." (PMID 24058639, 2013). "Fusion of the EWS gene to FLI1 produces a fusion oncoprotein that drives an aberrant gene expression program responsible for the development of Ewing sarcoma." (PMID 23894528, 2013). "More recently, it was also described the possibility of reducing the Myc oncogene expression in Ewing sarcoma cell by siRNA targeting of EWS/FLI1." (PMID 23329308, 2013). "Originally, Fli-1 was discovered as a common retroviral insertion site in Friend Murine Leukemia Virus-induced erythroleukaemia and subsequently as a common rearrangement in human Ewing’s sarcoma resulting in an EWS/Fli1 fusion product." (PMID 23667468, 2013). "Alterations in miR expression as a function of EWS/Fli1 or/and presumed cell of origin in Ewing sarcoma." (PMID 23543617, 2013). "Given that FLI-1 inhibitors have already been identified using human Ewing’s-sarcoma and erythroleukaemic cell lines, the Fli-1 mouse model developed here should be informative in elucidating pathways critical for inhibiting Fli-1-induced T cell proliferation." (PMID 23667468, 2013). "It was also described a novel peptide, defined ESAP1, able to bind EWS/FLI1 chimeric protein, with high affinity, altering cell-cycle process in Ewing sarcoma cells." (PMID 23329308, 2013). "Time-course experiments confirmed that LOX is a gene downregulated by EWS/FLI1, since LOX mRNA levels were significantly upregulated upon EWS/FLI1 knockdown in the A673 Ewing sarcoma cell line." (PMID 23750284, 2013). "Many of these candidates also corresponded to known gene fusions, including EWSR1/FLI1 in Ewing sarcoma and ABL1 rearrangements in several leukemia samples." (PMID 23637631, 2013). "In this case, LOX re-expression should antagonize, at least in part, the transforming properties of EWS/FLI1 in Ewing tumor cells." (PMID 23750284, 2013). "NKX2.2, a target gene upregulated by EWS/FLI-1, acts as a transcriptional repressor in Ewing's sarcoma cells." (PMID 22523703, 2012). "Transfer of EWS/FLI-1 gene into murine bone marrow cells and murine mesenchymal cells results in small round cell phenotype tumors histologically similar to Ewing's sarcoma." (PMID 22523703, 2012). "Lee AF showed that, in contrast to Ewing sarcoma, small cell osteosarcoma and mesenchymal chondrosarcoma lack FLI-1(Friend leukemia virusintegration-1) immunoreactivity." (PMID 22999069, 2012). "Strikingly, EWS/FLI1 has been found to induce the expression of EZH2 by direct binding to its promoter in both Ewing's sarcoma cell lines and human MSCs." (PMID 21609503, 2011). "The EWS/FLI-1 fusion is required for Ewing's sarcoma oncogenesis, as inhibition of its function results in the loss of transformation of ESFT cells." (PMID 21471610, 2011). "Detection of FLI-1, a nuclear protein that is involved in cell proliferation and tumourigenesis, is also useful in the diagnosis of Ewing's sarcoma." (PMID 22613930, 2011). "The KRAB/FLI-1 repressor also suppressed the tumorigenic phenotype of a human Ewing's sarcoma cell line." (PMID 12556973, 2003). "Eighty per cent (12/15 cases) of the Ewing tumours exhibited a positiveimmunoreactivity for the FLI1 antibody." (PMID 18521261, 1999). "Recently, Ewing's tumours have been shown to carry specific hybrid transcripts resulting from the fusion of the EWS gene with FLI-1 or ERG genes." (PMID 7599072, 1995).
Ewing sarcoma (continued). "However, CRISPR/Cas9-mediated gene editing can exhibit off-target effects, and thus, precise regulation of Cas9 expression in target cells is essential to develop gene-editing strategies to inactivate EWSR1 : : FLI1 in Ewing sarcoma cells." (PMID 40089636, 2025). "Identifying an EWSR1/FUS::FLI1 gene fusion is pivotal in confirming Ewing’s sarcoma." (PMID 40860805, 2025). "Notable examples include iCBP4 (derived from CCS1477), which selectively targets EP300/CBP in Group 3 MB, and the bromodomain inhibitor iP300w, which prevents P300/CBP-mediated histone acetylation, thereby disrupting EWS::FLI1-driven oncogenic signaling in Ewing sarcoma." (PMID 41228232, 2025). "Indeed, EZH2 is a well-known directly activated target of EWSR1::FLI1 that blocks neuroectodermal and endothelial differentiation in Ewing sarcoma." (PMID 41085408, 2025). "Notably, these two genes exhibit a moderate effect size as compared to EWSR1::FLI1, which ranks as the top Ewing sarcoma dependency in DepMap." (PMID 41444391, 2025). "Of note, IGFBP3 is also up-regulated in Ewing sarcoma cells after suppression of the EWS::FLI1 fusion, indicating that it may be a more common downstream effector of oncogenic transcription factors in mesenchymal malignancies." (PMID 40901948, 2025). "Both fusion proteins FUS-DDIT3 and EWSR1-FLI1 were shown to interact with the SWI/SNF CRCs in MLS 402-91 (myxoid liposarcoma) or EWS TC‐71 (Ewing sarcoma) cell lines, with each line carrying different FET oncogenes with simultaneous lack of expression of normal DDIT3 or FLI1." (PMID 40065228, 2025). "The most common fusion gene in Ewing sarcoma are EWSR1::FLI1 (85%) followed by EWSR1::ERG (10%)." (PMID 40666501, 2025). "Ewing sarcoma are potentially dually vulnerable to transcriptional CDK inhibition: ubiquitous binding of EWSR1::FLI1 at promoter sites results in widespread enhancer re-programming and transcriptional addiction, and the EWSR1::FLI1 transcript itself is relatively long, at more than 4 kb in length." (PMID 38775200, 2024). "Thus, in cases where a small round cell tumor is present where Ewing’s sarcoma is prevalent, such as the bone marrow, the diagnosis is skewed toward Ewing’s sarcoma when based solely on FLI-1 expression." (PMID 38280044, 2024). "Notably, Ewing sarcoma cells tend to demonstrate heterogeneity between EWSR1/FLI1 high and EWSR1/FLI1 low states, and the latter cells have a stronger propensity to metastasize." (PMID 39594644, 2024). "The best studied among all of these fusion proteins is EWSR1::FLI1, found in Ewing sarcoma." (PMID 38611033, 2024). "Additionally, copy number variations (CNVs) and fusion genes, such as the EWSR1/FLI1 fusion gene in Ewing sarcoma, play a crucial role in tumorigenesis." (PMID 39309469, 2024). "Moreover, a microarray analysis in Ewing sarcoma A673 cells revealed that depletion of endogenous EWSR1::FLI1 by retroviral siRNAs upregulated 320 genes and downregulated 1151 genes, among which NKX2.2 was reported as a critical EWSR1-FLI1 downstream target." (PMID 36672331, 2023). "The dependency on a complex involving EWSR1::FLI1, in particular in the context of a specific chromatin or developmental state, may contribute to the differential sensitivity of Ewing sarcoma cell lines to MS0621 compared to cells of other lineages." (PMID 36793594, 2023). "Recently, neo-transcripts have also been identified from silent genome regions uniquely activated by the EWSR1::FLI1 fusion, suggesting these neo-genes might be targetable for Ewing sarcoma treatment." (PMID 36672331, 2023). "Notably, DAX-1 expression was shown to depend on EWS/FLI1 expression in the A673 Ewing sarcoma cell line when EWS/FLI1 was knocked down." (PMID 37894854, 2023). "Furthermore, the depletion of Fli1 in Ewing’s sarcoma cells leads to the disappearance of PARP-1 expression." (PMID 37686260, 2023). "Together, EWSR1::FLI1 utilizes at least three distinct mechanisms to promote Ewing sarcoma growth." (PMID 36672331, 2023).
Ewing sarcoma (continued). "The pivotal role of DAX-1 expression in EWS/FLI1-mediated oncogenesis suggests that targeting DAX-1 could be a compelling therapeutic strategy for Ewing sarcoma." (PMID 37894854, 2023). "NKX2-2 is upregulated in Ewing sarcoma due to the presence of the EWS/FLI1 fusion protein." (PMID 37894854, 2023). "The chimeric EWSR1::FLI1 transcription factor is the main oncogenic event in Ewing sarcoma." (PMID 37511533, 2023). "The main objective of this study was to identify genes that were downregulated by EWSR1::FLI1 in Ewing sarcoma that could be potentially relevant for the tumorigenesis process." (PMID 37511533, 2023). "CD44s is upregulated upon EWSR1::FLI1 knockdown in the A673 Ewing sarcoma cells." (PMID 37511533, 2023). "FLI1 staining in nuclei is more specific for clinically defining Ewing sarcoma." (PMID 36672331, 2023). "This discovery raises the enticing possibility that disrupting the EWS/FLI1-DAX-1 interaction could open up new therapeutic avenues for Ewing sarcoma treatment." (PMID 37894854, 2023). "While DNA damage, such as radiation therapy, is the focus of this mini-review, the impact of other novel agents, such as tyrosine kinase inhibitors, agents targeting EWSR1::FLI1, etc., on the Ewing sarcoma TIME are also worthy of exploration and represent a limitation of this mini-review." (PMID 36483025, 2022). "In the prior sections we have described the existence and phenotypic characteristics of EWS::FLI1 “high” and “low” cell populations in Ewing sarcoma and broadly summarized what is currently known about the complex network of cell intrinsic and extrinsic factors that modulate these states." (PMID 36505823, 2022). "The EWS-FLI1 fusion protein, consisting of the EWSR1 gene and the FLI1 gene, which is caused by chromosomal translocation, is detected in more than 85% of cases in Ewing’s sarcoma." (PMID 36194562, 2022). "IHC detection of FLI-1 is more specific for Ewing sarcoma than is CD99." (PMID 35372059, 2022). "Next, we aligned the copies of EWS/FLI‐1 mRNA (obtained by following the optimized workflow) with Positron Emission Tomography – Computed Tomography (PET/CT) images in order to monitor the dynamic changes in Ewing sarcoma in relation to treatment response." (PMID 35486030, 2022). "EWS::FLI1 translocation accounts for 85% of Ewing sarcoma cases." (PMID 36533189, 2022). "Due to the reliance of EWS::FLI1 on chromatin remodeling complexes, there is great interest in targeting Ewing sarcoma and the fusion specifically using epigenetic drugs including agents that inhibit HDACs (HDACi), bromodomain proteins (BETi), LSD1 (LSD1i), and KDM3A (JIB-04)." (PMID 36505823, 2022). "Interestingly, loss of STAG2 in Ewing sarcoma cells results in impaired loop extrusion and alters promoter-enhancer interactions which impedes the EWS::FLI1-dependent transcriptional program." (PMID 36505823, 2022). "Ewing sarcoma is a pediatric bone cancer that expresses the chimeric protein EWSR1/FLI1." (PMID 33293370, 2021). "Subsequent studies demonstrated that 85% of Ewing sarcoma patients have tumors that express the EWSR1/FLI1 fusion gene, while the remaining patients have tumors that express fusion genes composed of EWSR1 and other ETS transcription factors (ETV1, ETV4, ERG, and FEV1)." (PMID 33293370, 2021). "This study supports the therapeutic targeting of OTUD7A as a novel strategy for Ewing sarcoma bearing EWS–FLI1 and related fusions, and may also be applicable to other cancers dependent on aberrant FLI1 expression." (PMID 34060252, 2021). "One such fusion, EWSR1/FLI1, typifies Ewing sarcoma as it is found in 85% of cases." (PMID 34409300, 2021). "Moreover, recent studies have surprisingly revealed that EWS/Fli1, the driver oncofusion in this disease, inhibits, rather than promotes, many important metastatic properties in Ewing sarcoma." (PMID 33196691, 2020). "However, the small molecule ERG/FLI1 inhibitor TK216 tested here has entered a phase 1 study in Ewing sarcoma." (PMID 33218352, 2020).